JUN (Jun proto-oncogene, AP-1 transcription factor subunit)
Diseases named in the same sentence as JUN in open-access papers (continued):
Sharing a sentence is not in itself a finding about the gene and the disease.
tumor (continued). "Elevated MT-CO2 increases flavin adenosine dinucleotide (FAD) levels in activating lysine-specific demethylase 1 (LSD1) to epigenetically upregulate JUN transcription, consequently promoting glutaminase-1 (GLS1) and glutaminolysis for tumor cell survival." (PMID 39747079, 2025). "Tumor-specific CD4 + T cells showed higher expression levels of chemokine CXCL13, immune regulators FOS and JUN, and exhaustion markers TIGIT." (PMID 39033098, 2024). "Tumor-specific CD8 + T cells exhibited higher expression levels of cytotoxicity-related genes IFNG and GZMK, immune regulators FOS and JUN, and exhaustion markers TIGIT and PDCD1." (PMID 39033098, 2024). "Taken together, our study robustly substantiated the promising anti‐tumour activity of OPD' in ATC and elucidated the mechanism that OPD' bind with JUN to repress RGS4 transcription, consequently inducing cell cycle arrest and apoptosis in ATC cells." (PMID 39153211, 2024). "The peri-necrotic zone and pseudo-palisading cells around necrosis showed significantly higher mRNA levels of JUN, JUNB, FOS, and FOSL2 compared to other regions of the tumor, such as the leading-edge, infiltrating tumor, and cellular tumor." (PMID 39257581, 2024). "While JUND and JUNB demonstrate tumor-suppressive activity, JUN and FOS frequently display oncogenic characteristics when acting as either tumor suppressors or oncogenes in cancer." (PMID 38674385, 2024). "The LGALS3/JUN/ITGB1/SPP1 genes were highly expressed in MES-like GBM cells, and the expression of these genes was significantly upregulated with tumour progression." (PMID 39629136, 2024). "We found that the macrophage chemotactic factor SPP1, which is one of the largest secreted proteins in the tumour microenvironment and can be upregulated by the ERK/JUN signalling pathway 37, was significantly upregulated in MES-like GBM cells." (PMID 39629136, 2024). "We also identified well-known transcription factors, such as JUN and STAT3, which were found to be targeted and regulated by m6A during tumor progression and tumor immunity." (PMID 38970366, 2024). "In the Huh7 tumor cells, the JUN and PGF expression were significantly up-regulated and the JUN exhibited a more significant increase (p < 0.05), indicating that these genes played an important role in promoting cancer progression." (PMID 39484208, 2024). "Other major potential tumor growth factors, such as POU2F2, RUNX1, ERG, REL, and JUN, were also relatively increased in the low TEX-score group." (PMID 38629071, 2024). "Two sets of genes were chosen, PDGFRA, Lin28A, THBS1, JUN, PLCB1 and GABRA5, which were found to be up- and down-regulated, respectively, in support of tumour cell proliferation." (PMID 38000389, 2024). "YAP5SA livers showed a multifocal tumor growth with large tumor lesions whereas those lesions were barely detectable in YAP5SA-JUN WT/M14 livers, demonstrating that JUN’s repressive effect on YAP activity potently interferes with liver tumor growth." (PMID 39210147, 2024). "Compared to the control group after 48 h of treatment with TGT, the expression of genes JUN, TYMS, HSP90AA1, HDAC1, CDK1, and ESR1 was downregulated, which showed inhibitory effect on tumor cell proliferation." (PMID 38297292, 2024). "A comparison of EGR1, FOS, IER2, JUN, KLF6, MYC, and FOSL2 gene expression in 481 tumor samples revealed that individual tumors vary substantially in the expression of all analyzed genes." (PMID 39436655, 2024). "We demonstrated that the tumor suppressive is mediated by both positively and negatively acting downstream effectors, including CBX6, TRIB3, ETV4 and FOS/JUN, where the first two also affect the differentiation status of Lp30 AML." (PMID 36631623, 2023). "While FOS (c-Fos) and JUN (c-Jun) are known to induce T cell activation, FOS previously has been shown to suppress T cells through PDCD1 and promote tumor progression." (PMID 36305874, 2023).
tumor (continued). "Whereas JUN, HSPH1, HSPA8, HSPA6, HSP90AB1, and EGR1 were found to be the DEGs in both Tumor vs. normal and tumor vs. metastasis group." (PMID 37335089, 2023). "The EMT tumor population showed increased binding accessibility for known positive regulators of EMT, such as TWIST1 and JUN." (PMID 36973268, 2023). "The combined activation of EGFR and Hh pathway synergistically promote tumor formation, in part due to EGFR-GLI regulated RAF/MEK/ERK target JUN/AP-1 expression." (PMID 37853413, 2023). "Twenty-eight of 32 TCGA cancer types had increased expression of both JUN and PRPS1 in comparison with their respective normal tissues, indicating the importance of JUN and PRPS1 in tumorigenesis and tumor progression." (PMID 37909334, 2023). "TalaA downregulated the phosphorylation of a series of transcription factors, including JUN, NFATC1, EIF4EBP1, ABL, RPS6KB1, and EIF4ENIF1, most of which play pivotal roles in cell proliferation and tumor progression." (PMID 37866481, 2023). "This study established a seven-gene profile (FGG, C3, FGA, JUN, CST3, CPSF4, and HIST1H2BH) prognostic stratification system demonstrated in LUSC based on Tumor Progression, Immune Infiltration, and Stem Index." (PMID 37841237, 2023). "MSI2 binds the internal ribosome entry site (IRES)-containing oncogene mRNAs including MYC, JUN and VEGFA as well as HCV IRES to increase their synthesis and promote self-renewal and tumor-initiation at the post-transcriptional level." (PMID 37117191, 2023). "Factors released from tumor cells feed forward to increase activation of NF-κB (NF-κB1), STAT3, and AP1 (JUN, JUNB, and FOS) in surrounding cells." (PMID 36134665, 2022). "Genes from FOS-JUN modules (FOS, JUN, and ERG1), MAPK/ERK, PI3K-AKT and JAK/STAT pathways, and IGF1 involved in tumor growth and resistance to AI, were upregulated in both studies." (PMID 34965950, 2022). "A multivariate analysis was performed including tumor and nodal classification, grade, PAM50 subtype, NF1, KRAS, RAF1, and JUN alterations." (PMID 36358725, 2022). "Consistent with the previous conclusion that the EMT signature is a potential factor for tumor invasion and metastasis, the genes related to the EMT signature, including MGP, GAS1, and JUN, were found in Scissor+ cells of metastatic HGSOCs lesions." (PMID 35935940, 2022). "The mRNAs of JUN, IL-6 and PPARG were reduced in tumor cells and up-regulated by Chidamide treatment." (PMID 36425653, 2022). "AP-1 transcription factors are dimers of basic region-leucine zipper (bZIP) proteins belonging to the JUN, FOS, MAF and ATF sub-families and play important roles in cellular proliferation, survival, locomotion and tumor biology." (PMID 35267426, 2022). "Some studies have reported that the N‐terminal kinase JUN N‐terminal kinases (JNK) of JUN can activate the MAPK signaling pathway to regulate drug sensitivity and tumor resistance." (PMID 36176734, 2022). "The PPI network showed that CASP3, JUN, TNF, MMPs, and MAPK are the core hubs of XFZYD in tumour treatment." (PMID 35903326, 2022). "Dimers of FOS (c‐FOS, FOS‐B, FRA‐1/FOSL1 and FRA‐2/FOSL2) and JUN (c‐JUN, JUN‐B, and JUN‐D) build the AP1 complex, which can drive tumor progression and treatment resistance." (PMID 35604882, 2022). "In tumor cells, EGF stimulation resulted in overexpression of JUN/AP1 while inhibition of AKT downregulated it." (PMID 35269445, 2022).
tumor (continued). "We noted that the DEGs between the two T-cell clusters were consistent with the DEGs identified between ERG+ and ERG− tumor cells, with FOSB, FOS, and JUN overexpressed in ERG+ tumor cells while CXCR6 and DUSP4 were overexpressed in ERG- tumor cells." (PMID 35013146, 2022). "The SPINK1 general cancer pathway and HGF signalling were activated in G3 cells in which the tumour malignancy‐related genes RASD1, PIK3R1, JUN, and FOS were significantly upregulated, indicating that G3 promotes malignant progression in GC." (PMID 35184420, 2022). "AP-1 is a dimeric complex that includes the JUN, FOS, ATF and MAF proteins that form diverse homodimers and heterodimers in regulating oncogenic and tumor-suppressive activities." (PMID 35022313, 2022). "(E) Immunoblot analysis of LADC tumours probed for USP28, c-MYC, c-JUN, SFTPC, cleaved caspase-3 (CC3)." (PMID 34636321, 2021). "Studies have also shown that phosphorylation of cellular JUN regulates the secretion of chemokines by macrophages in LIHC-bearing liver, and affects the recruitment of regulatory T cells and tumor progression." (PMID 34938730, 2021). "Integrative analysis of multiomics data identified EGFR, JUN, MYC, FN1 and SERPINE1 as key modulators of the tumour immune microenvironment and potential targets for combination therapies which was validated in two validation sets." (PMID 33971902, 2021). "Usp28 downregulation by shRNA resulted in a significant reduction in c-MYC, c-JUN, and Δp63 protein levels in LSCC primary tumour cells and reduced LSCC cell growth." (PMID 34636321, 2021). "The transcription factor JUN was reported to activate the transcription of the promoters of several key UPR effectors, such as XBP1 and ATF4, to inhibit tumour cell apoptosis." (PMID 33971902, 2021). "Upregulated within the tumor-infiltrating CD4+ T cells were heat shock proteins (HSPA1A and HSPA1B), Jun and FOS constituents (FOS, JUN, and JUNB), MHC-II molecules (HLA-DRB), and secreted molecules (CCL5, GZMA, and GZMK)." (PMID 33504936, 2021). "As shown in the volcano plot, SU decreased GZMB expression and upregulated genes related to inflammatory activation (FOS, JUN, NFKBIA, DUSP2, JAK1, PIM1), tumor immunity (CD47, PCBP2, EIF5A, PDIA3, EGR1), and DNA damage (H2AFX, DDIT3, GADD45B)." (PMID 34824394, 2021). "Inserts showing c-MYC+, c-JUN+, Δp63+ LSCC tumours in mice receiving vehicle but partial positive or negative LSCC lesions in mice receiving FT206." (PMID 34636321, 2021). "siRNA-mediated USP28 but not USP25 depletion, and USP28 inhibitor treatment, considerably reduced protein levels of Δp63, c-JUN, and c-MYC and impaired growth in human LSCC tumour cells." (PMID 34636321, 2021). "Actually, previous researchers have identified lncRNAs as prognostic markers of PTC, such as TTTY10, LINC00284, RBMS3-AS1, and ZFX-AS1 and five lncRNAs of PPARG, E2F1, CCND1, JUN, and EZH2 for predicting tumor recurrence in PTC." (PMID 34721037, 2021). "(D) Quantification of c-MYC+ (LADC n = 33, LSCC n = 34), c-JUN+ (LADC n = 33, LSCC n = 33), and Δp63+ cells (LADC n = 41, LSCC n = 41) in LADC and LSCC tumours." (PMID 34636321, 2021). "Both precancerous and tumor cells can exploit deregulated cytokines in the TME, promoting growth through activation of downstream signaling, such as the ERK, JUN, and NF-κB pathways." (PMID 31941995, 2020). "The specific mechanism has been demonstrated that EBV-miR-BART13-3p directly targets tumor suppressor gene ABI2, which consequently up-regulates the c-JUN/SLUG signaling, eventually leading to epithelial-mesenchymal transformation (EMT) and tumor metastasis." (PMID 31907338, 2020).
tumor (continued). "As suggested in murine model, ALK promotes the expression of activator protein 1 family members JUN and JUNB, which subsequently promote tumor dissemination through PDGFRB regulation." (PMID 32637355, 2020). "FBW7 degrades some proto‐oncogenes that play a role in cell growth and division pathways, including JUN, Notch, MYC and cyclin E.47FBW7 is also a tumour suppressor and its regulatory network is disrupted in many human malignancies." (PMID 32352219, 2020). "CXCL5, ELN, JUN, and FGFR4 were highly expressed in normal tissues, while PLAU, RNASE7, JAG1, SPP1, and TNFRSF18 were highly expressed in tumor tissues." (PMID 32699529, 2020). "Thus, JUN could promote tumorigenesis and tumor development." (PMID 32863767, 2020). "Some tumor-related genes such as FOX, NFATC1 and JUN were highly expressed in Nthy-ori 3-1 with lentivirus vector PDS159-FAM172A and FTC tissues compared with Nthy-ori 3-1 with empty vector and peri-carcinoma tissues." (PMID 33095186, 2020). "Among these altered genes, some oncogenes, such as PON2 and CD34, were downregulated, and some tumor suppressors, such as KLF6 and JUN were upregulated." (PMID 31723124, 2019). "Gene ontology analysis of these DEGs showed that in advanced stage tumours, pathways such as cell adhesion (VCAN), ECM receptor interaction (COL1A2, COL3A1, ITGA11, and TNN) and pathways in cancer (JUN, and MYC) getting deregulated." (PMID 31292488, 2019). "The end targets of these pathways, including cytokines (IL1A/B, IL6, IL8, IL18) and genes related to cell proliferation (JUN, SRF), were upregulated, suggesting that the activation of these TLRs leads to tumor growth." (PMID 29912993, 2018). "FBW7 is considered a tumor suppressor targeting several dominant oncogenes such as c-MYC, CYCLIN E, c-JUN, and NOTCH for proteasomal degradation." (PMID 29880484, 2018). "In general, c-JUN acts as an oncogenic driver, whereas JUNB and JUND have tumour suppressive effects." (PMID 29597249, 2018). "Consistent with our findings, reverted tumours showed upregulated expression of MAPK9 expression, a negative regulator of JUN." (PMID 29662623, 2018). "Concordantly, TFF3 expression in EC tumour samples positively correlated with the levels of SP1, and the activity and levels of phospho c-JUN." (PMID 29100386, 2017). "Immunohistochemical analysis of the tissue micro array derived from these patients established the functional correlation between the decreased expression of tumor suppressive miRNAs and their target oncogenes: ERBB2, EGFR, EPHA2, BAX, GNA12, GNA13, and JUN." (PMID 28740575, 2017). "GSK3 plays a role in the control of several regulatory proteins including the proto‐oncogene JUN, and in the WNT and PI3K signaling pathways that are critical in tumor progression." (PMID 28035236, 2017). "Depletion of JUN and JUNB or disruption of TAK1-RELA signaling blocked the cytokine-mediated induction of MMP9 in tumor cells." (PMID 28423685, 2017). "A number of TFs were significantly altered in two or more tumour types, including ZEB1, JUN, ELK1, FOXM1, while others were limited to a single type, such as FOXD1 in HNSC and FOXL1 in KIRC." (PMID 28139702, 2017). "Depletion of JUN and JUNB or RELA in tumor cells blocked the cooperative induction of MMP9 by the cytokines." (PMID 28423685, 2017). "An additional level of complexity is illustrated by molecular crosstalk between YAP/TAZ-TEAD and JUN/FOS –AP-1 DNA binding sites acting at cis-regulatory distal enhancers of target genes involved in cell cycle control and tumor growth." (PMID 27527859, 2016). "MELK is thought to bind and activate transcription factors c-JUN and FOXM1 and play a role in maintaining tumor initiating cells." (PMID 27574806, 2016).
tumor (continued). "Two components of AP-1, c-JUN, and c-FOS, are well known as oncoproteins, but in some cases they can suppress tumor formation." (PMID 27270647, 2016). "Other genes similarly regulated include DUSP1, EGR1, EGR2, JUN, and NR4A1, which are components of the TTP-low tumor gene signature, again linking TTP levels and innate immunity." (PMID 25541715, 2014). "Several candidate genes, such as MYCN, ERBB3, JUN, and IGFBP5, were also significantly upregulated, which keeps the tumor in a proliferative state." (PMID 22690114, 2012). "Croce and his group (2009) described an increase of miR-221 and -222 in NSCLC and HCC through c-JUN induction and PTEN and TIMP3 tumor-suppressor targeting." (PMID 21711453, 2011). "As the most prominent tissue‐resident ILC3 subsets in tumour, ILC3‐HSPA1B is distinguished by upregulated expression of cell stress‐related genes (e.g., HSPA1B, HSPA1A, and JUN), all of which have been reported to be involved in cellular stress responses and adaptive mechanisms." (PMID 41527493, 2026). "Consistent with observations in APAs, the phosphorylated forms of FOS and JUN were largely absent in the tumor tissue but remained detectable in both zona glomerulosa and zona fasciculata cells of the non-neoplastic adjacent cortical regions." (PMID 41412035, 2025). "The downregulation of JUN and NFKB1 in mesenchymal subtypes may impair their ability to maintain tumor-suppressive functions, highlighting their potential role in driving BC progression." (PMID 40666524, 2025). "While the tumor-suppressive roles of TIAM1 and RAP1GAP have been previously established, our findings reveal that the overexpression of GPX3 and JUN significantly impairs the proliferative and migratory capacities of TC cells, underscoring their potential as therapeutic targets." (PMID 40092686, 2025). "Although JUND and JUNB are often credited with similar tumor promoter/suppressor roles regarding the cellular context, the vast majority of published data (including those in cancer of non-prostatic origin) credit JUND/JUNB with opposing roles to c-JUN." (PMID 41020863, 2025). "This suggests that TIAM1 may function as an oncogene, while RAP1GAP, JUN, and GPX3 might act as tumor suppressors." (PMID 40092686, 2025). "This transformation could be associated with the expression levels of genes such as PDGFRB, PGF, JUN, and NR4A1, which play crucial roles in tumor development, angiogenesis, and cell proliferation." (PMID 39484208, 2024). "We now identify JUN as a component of a negative feedback mechanism with tumor suppressive properties to protect the organism from oncogenic YAP levels." (PMID 39210147, 2024). "Other studies implicate c-JUN and STAT3 in tumor suppressive functions, too." (PMID 39358322, 2024). "Additionally, rosmarinic acid complements the action by targeting MAPK1, IKBKB, JUN, and RELA to synergistically inhibit the proliferation of tumor cells and induce apoptosis." (PMID 39840098, 2024). "Our results similarly point towards a context dependent tumor-suppressive role, rather than a driving function of JUN in PCa progression." (PMID 38811984, 2024). "Both JUN and NRL were included in the GO terms related to development, prompting us to speculate that sunitinib may promote tumor differentiation via inactivation of MAPK activity in RB654 organoids." (PMID 36726110, 2023). "Meanwhile, tumor cells in the combination groups showed a higher rate of apoptosis as detected by the TUNEL assay, as well as higher acetylation status, ubiquitination level of HP1γ, suppressed HP1γ level and FOS, JUN and CD40 expression." (PMID 36894562, 2023). "Whole-exome sequencing showed that this tumor also harbored CDK4, TSPAN31, and JUN amplification." (PMID 37881487, 2023).